APOE (apolipoprotein E)
Diseases named in the same sentence as APOE in open-access papers (continued):
Sharing a sentence is not in itself a finding about the gene and the disease.
dementia (continued). "Further studies are needed to clarify if the amount of apoE in HDL containing or lacking apoC3 or apoJ is associated with dementia via brain-specific or systemic pathways." (PMID 32648923, 2020). "It showed an independent impact of APOE ε4, diabetes, depression, low fruit/vegetable consumption, and cognitive reserve (i.e., crystallized intelligence) on dementia or mild cognitive impairment incidence, approaching an overall PAF of 40% for modifiable factors." (PMID 32767997, 2020). "Obesity, and particularly central obesity (larger waist circumference), have been associated with dementia incidence independent of demographics, lifestyle behaviors, APOE-ε4, hypertension and diabetes." (PMID 33050383, 2020). "Multivariable logistic regression analysis revealed that ammonia concentration was associated with the presence of dementia, independent of age, sex, education years, ApoE ε4, enterotypes (either enterotype I or III), and risk factors." (PMID 32424166, 2020). "Moreover, subjects with different dementia types and with one or two copies of the ε4 allele of the APOE gene exhibit decreased expression levels of serum apolipoprotein E with regard to both earlier onset of symptoms and deposits of beta-amyloid plaques." (PMID 30897703, 2019). "In contrast, APOE ε4 carriers may benefit from high-dose ω3 supplementation in pre-dementia stages, but this intervention needs to be optimised, maybe by taking advantage of advances in brain imaging techniques." (PMID 30691140, 2019). "We found a modifying effect of ApoE-ε4 on circulating IGF-I receptor stimulating activity at baseline and an interaction on the relation between IGF-I receptor stimulating activity and the risk of dementia." (PMID 30809143, 2019). "Similarly, the prevalence of dementia in APOE ε3ε3 persons with high PBV values was only 5.7% versus 6.7% for APOE ε2ε3 persons." (PMID 31022959, 2019). "Previous studies have shown that APOE genotype influences dementia risk in DS in much the same way as in the non-DS population." (PMID 30452522, 2019). "Verhaaren and colleagues included 5171 middle-aged and older people without dementia to investigate the association of weighted PGSs constructed with 12 AD risk SNPs (including APOE ε4) with general cognition, memory, and possessing speed." (PMID 30866553, 2019). "Consequently, APOE ε2ε3 lowered the probability of dementia by an age equivalent to approximately 16 years compared to APOE ε3ε4/ε4ε4 carriers." (PMID 31022959, 2019). "Stepwise multivariable logistic regression analyses (model 1 included enterotype I and model 2 included enterotype III) showed that female sex, enterotype, ApoE ε4, SLI or CMBs, high VSRAD score, and the use of anti-dementia drugs are independently associated with the presence of dementia." (PMID 30700769, 2019). "Also, ApoE genotype is related to a level of intellectual disability, and presence of dementia in Down syndrome." (PMID 31514272, 2019). "Our study shows that most adults with DS now have dementia when they die and are affected by some of the same factors associated with dementia (such as APOE genotype) as we see in the non-DS population." (PMID 30452522, 2019). "To confirm our hypothesis, we examined the ApoE genotype and gait velocity in a well-characterized large sample of community-dwelling older adults free of dementia." (PMID 31572165, 2019). "Patients who progressed to dementia were also more often APOE ε4 carriers." (PMID 31805990, 2019). "Our work also indicated that the proposed surface-based hippocampal morphometry is capable to detect hippocampal deformations related with APOE-e4 before dementia symptom appearance and may serve as a valuable preclinical AD imaging biomarker." (PMID 30852398, 2019).
dementia (continued). "Our study suggests that the ApoE-ε4 genotype modifies the relationship between IGF-I receptor stimulating activity and dementia and elevated IGF-I receptor stimulating activity levels mark a compensatory response to neuropathological changes associated with the ApoE-ε4 genotype." (PMID 30809143, 2019). "Higher PBV levels (>1 SD) appeared to modulate the negative effects of age and APOE ε4 allele on the probability of dementia." (PMID 31022959, 2019). "However, the link between APOE and other forms of dementia such as vascular dementia is still inconclusive, more so in the Indian population." (PMID 31998815, 2019). "Results from cohort studies are contradictory, reporting that physical exercise is both protective for cognitive decline in APOE ε4 carriers as well as lowering the risk of dementia in APOE ε4 non-carriers." (PMID 30611286, 2019). "We found similar associations of alcohol use and risk of all-cause dementia or AD in analyses restricted to APOE E4 noncarriers." (PMID 31560382, 2019). "This could mean that these pathways are already changed or dysregulated at birth in APOE ε4 carriers, indicating that these individuals subsequently have a lower resilience to the development of dementia." (PMID 30811346, 2019). "This study has several limitations including the small number of AD cases and controls and the paucity of clinical details relating to the de-identified AD cases, such as dementia severity, disease duration and APOE genotype, that would be of interest for further analysis." (PMID 31521199, 2019). "When dementia cases were included, the following variables were found to contribute to age 79 IQ: age 11 IQ (42.4% of variance); fitness (3.1%), social class (1.2%), sex (0.7%), and APOE ε4 (0.6%)." (PMID 29745686, 2018). "The association for shift work and night work duration with dementia incidence was generally more pronounced in carriers versus non-carriers of APOE ε4." (PMID 30076495, 2018). "Similarly, longitudinal analyses have also indicated that mid- to late-life trajectories of cholesterol levels are related to both APOE genotype and dementia status." (PMID 30167451, 2018). "T2DM patients carrying one or two ApoE ε4 allele had a significantly higher risk of dementia than those who were negative for T2DM or ApoE ε4 allele." (PMID 29896424, 2018). "Taking all of these considerations into account, we hypothesized that positive age beliefs will protect older individuals, including APOE ε4 carriers, from developing dementia." (PMID 29414991, 2018). "Cumulative incidence graphs supported these findings, with an increased risk of dementia for APOE ɛ4 carriers compared with non-carriers." (PMID 30180830, 2018). "The association between lower levels of Aβ and risk of dementia among APOE-ε4 carriers and noncarriers appeared similar, such that lower levels of Aβ1–38, Aβ1–40, and Aβ1–42 were associated with increased risk of dementia in both strata." (PMID 29960604, 2018). "Two of 3 carriers were heterozygous for APOE ε4 allele and do not report any familial history for dementia." (PMID 29544907, 2018). "We also found an association of the APOE £4 genotype with dementia that was independent of Aβ plaque and tau NFT pathology." (PMID 30473927, 2018). "APOE ε4 appeared to modify the association between night work and dementia risk, but not the association between shift work and subsequent dementia." (PMID 30076495, 2018). "Therefore, we perform a combined analysis with age at PD diagnosis, age at which the dementia test was performed, APOE status, and cohort included as covariates." (PMID 29692703, 2018). "Among members of the APOE ε4 group, those with positive age beliefs at baseline had a 2.7% risk of developing dementia, compared to the 6.14% risk for those with negative age beliefs, in the 4 years studied." (PMID 29414991, 2018).
dementia (continued). "For APOE ε4 carriers with positive age beliefs had a risk of developing dementia that is similar to the risk of their same-aged peers without APOE ε4, regardless of age beliefs." (PMID 29414991, 2018). "In our sample, the dementia conversion rate due to negative age beliefs was within .03% of the dementia conversion rate due to APOE ε4, a well-established risk factor for dementia." (PMID 29414991, 2018). "Individuals with incident dementia were significantly older at baseline, with fewer years of education, were more likely to be carriers of the APOE ε4 allele, and had higher initial systolic blood pressure than those who were not diagnosed with dementia." (PMID 29330643, 2018). "Interestingly, apolipoprotein E ε4 (APOE ε4), which is a genetic risk factor for AD and dementia with Lewy bodies, can cause PP2A inactivation by downregulating the expression of PPP2R5E, a regulatory subunit of the PPP2R5 subfamily." (PMID 29950985, 2018). "The reduction of stress by positive age beliefs could potentially contribute to a lower incidence of dementia among older individuals in general and specifically among those with APOE ε4." (PMID 29414991, 2018). "We further aimed to determine the effect of a clinical diagnosis of dementia and APOE genotype on stage, given that APOE genotype is strongly associated with age of onset of dementia due to AD, with the e4 allele driving earlier onset and increased risk and the e2 allele reducing risk." (PMID 29928657, 2018). "Since apoE genotype may be a significant factor in the development of dementia, as a sensitivity analysis we repeated these analyses in the subgroup where apoE genotyping was available, by adding apoE genotype as a confounder in fully adjusted models." (PMID 28763509, 2017). "We hypothesized that SMD with an AD-like pattern of brain atrophy would have worse cognitive performance at baseline, increased neocortical amyloid burden, higher frequency of the APOE ε4 allele, and higher rate of progression to MCI or dementia." (PMID 28287184, 2017). "Family history of dementia is also associated with an increased AD risk, independent of carrying the ApoE ε4 allele (Scarabino, Gambina, Broggio, Pelliccia, & Corbo, 2016)." (PMID 29201555, 2017). "Moreover, Apo(a) can alter ApoE isoform metabolism, which suppresses changes related to the development of dementia." (PMID 28251161, 2017). "Five-year cumulative incidence of dementia by baseline age and APOE-e4 dose." (PMID 28323826, 2017). "Lifetime (to age 80–85 y) cumulative incidence of dementia by baseline age and APOE-e4 dose." (PMID 28323826, 2017). "The data were analyzed to investigate whether the proteins were expressed together and in relation with metabolic disorders, dementia, Alzheimer's pathology and APOE genotype." (PMID 27106634, 2017). "On the basis of our regression findings, for APOE-e4/e4 homozygotes, the adjusted relative risk for MCI/dementia is 2.7 for NACC, 3.4 for the Framingham Heart Study, and 2.4 for the Rotterdam Study, so disclosing a relative risk of about 3-fold compared to the general population would make sense." (PMID 28323826, 2017). "With regards to the APOE polymorphism, the expression of metaflammasome proteins did not change the dementia risk conferred by the APOE genotype (data not shown)." (PMID 27106634, 2017). "Five-year cumulative incidence of MCI/dementia was low in the youngest age stratum, particularly in the cohort studies, although somewhat higher for APOE-e4-positive individuals, especially homozygote individuals (23% in NACC and 5%–6% in Framingham and Rotterdam)." (PMID 28323826, 2017). "Sociodemographics, clinical variables, and APOE genotype, according to dementia status (n = 1,092)." (PMID 28350821, 2017). "Previous studies have highlighted that a number of non-modifiable risk factors, such as age and apolipoprotein E genotype, were strongly associated with dementia." (PMID 28403222, 2017).
dementia (continued). "Focusing on these factors that may influence the progression we found significant differences in APOE 4 genotype (p = 0.02), so those with at least one AP0E4 positive allele have a higher risk of progressing to dementia, OR of 3,294 (95 % CI 1,174- 9,243)." (PMID 27260328, 2016). "The APOE ε4 allele is associated with depression, mild cognitive impairment (MCI) and dementia; however, the precise molecular mechanism through which ApoE4 influences the risk of disease development remains unknown." (PMID 27406263, 2016). "Our sensitivity analysis indicated that these effects were independent of dementia pathology: that is, the APOE e4 allele appeared to relate to normal, not just pathological, cognitive ageing." (PMID 27932854, 2016). "Our study provides informative data regarding ethnic differences in the association between APOE and non-communicable diseases or dementia." (PMID 27168072, 2016). "Previous results reporting on the significance of specific candidate genes such as angiotensin converting enzyme gene, alpha-1-antichymotrypsin or apolipoprotein E (APOE) gene as risk factors for dementia after stroke are not entirely in agreement." (PMID 26806700, 2016). "The differences in methodologies between mass spec based assays and immunoassays may explain why our study finds higher levels of apolipoprotein E in dementia compared to others." (PMID 26627638, 2015). "Thus, we provide analyses of a very old sample, screened for both dementia and preclinical dementia, which represents a group that has rarely been examined in the context of APOE and white matter microstructure." (PMID 26252210, 2015). "In contrast, APOE-4 positive subjects who were prescribed CCBs showed a significant protective effect and a trajectory to dementia equivalent to that of subjects without APOE-4 alleles or CCB use." (PMID 26221415, 2015). "Conversely, in the MIRAGE study, the influence of head injury onthe risk of dementia was greater among persons lacking APOE ε4 compared withthose having one or two APOE ε4 alleles." (PMID 29213985, 2015). "In a population-based studyin Northern Manhattan, New York42a history of TBI and inheritance of an APOE ε4 allele were associated with a10-fold increased risk of dementia while APOE ε4 in the absence of TBIresulted in only a 2-fold increased risk of dementia." (PMID 29213985, 2015). "Furthermore, an interaction between FTO and APOE was found, with increased risk for dementia for those carrying both FTO AA and APOE ε4." (PMID 26691922, 2015). "Lower white matter integrity may represent one of several mechanisms through which APOE affects PS performance in elderly persons free of dementia and preclinical dementia." (PMID 26252210, 2015). "Although genomic analyses have identified the apolipoprotein E (apoE) ε4 allele as a major risk factor for late-onset AD, cerebral small vessel disease (SVD) may also play a significant role in decline to dementia." (PMID 26161148, 2015). "This is consistent with the hypothesis that ApoE can affect neuronal repair early in life, well before the onset of the clinical signs and symptoms of dementia." (PMID 26287823, 2015). "The purpose of the current study was to investigate the extent to which white matter microstructure (FA and MD) mediates the association between APOE and PS in very old persons without dementia." (PMID 26252210, 2015). "Previous studies indicated that the APOE-ε4 allele exerts effects on the cognitive performance, including spatial attention and working memory in healthy middle-aged carriers without dementia." (PMID 26053677, 2015). "Individuals possessing one or more APOE ε4 alleles declined faster than those without APOE ε4, and individuals who had a family history of dementia in addition to one or more APOE ε4 alleles had the worst performance over time on average." (PMID 26102276, 2015).
dementia (continued). "Small lung volumes were prospectively associated with an increased risk for poor cognitive function and dementia in non-carriers of the APOE E4." (PMID 24571688, 2014). "When comparing ApoE ε4 allele carriers and non-carriers regardless of dementia status, subjects with one or two ε4 alleles presented with significantly lower CRP levels." (PMID 24804776, 2014). "The finding that there was a lack of association between the APOE-ɛ4 allele and dementia appears to be unique to the African population as the presence of this allele has been associated with a higher prevalence of AD in Caucasians and African Americans." (PMID 25177512, 2014). "One interpretation of our results could be consistent with Altmann's general findings: when APOE is removed from the AD-GRS, women's odds ratio for dementia decreases because APOE was the main driver of the association." (PMID 25328845, 2014). "In the Rotterdam Study on elderly individuals, APOE genotype did not modify associations of serum cortisol with dementia." (PMID 24735831, 2014). "The strong association of the AD-GRS without APOE with dementia probability in NHB is striking because the beta coefficients used to create the AD-GRS were largely drawn from studies of white populations." (PMID 25328845, 2014). "The APOE E4 effect on dementia has been reported to be stronger in Asian than in other ethnicities." (PMID 25530658, 2014). "We also show that the association at the APOE locus is similar to the one that occurs in AD, in accordance with previous studies, and that the SNCA and SCARB2 associations are different to the ones reported in PD and possibly PD with dementia." (PMID 24973356, 2014). "Adjustment for age and sex, or for age, sex, and ApoE ε4, nonsignificantly decreased the hazard ratio for the association between tremor and dementia (HR 0.50, 95% CI 0.21 to 1.20, P = 0.12; or HR 0.46, 95% CI 0.17 to 1.23, P = 0.12)." (PMID 26317006, 2014). "We have previously shown that in DS polymorphisms in PICALM and APOE are associated with AOO of dementia, and there is a nonsignificant trend in risk allele loading derived from AD meta-analysis." (PMID 24462566, 2014). "The clear implication of this pattern of incidence with age, is that the age of onsetof incident dementia cases is younger among those with one or more APOE ε4alleles, compared with those lacking an ε4 allele." (PMID 29213926, 2014). "Among NHB, a similar AD-GRS excluding APOE also predicts dementia." (PMID 25328845, 2014). "In addition, we assessed APOE, a gene that has been carefully investigated, particularly in patients with dementia." (PMID 25239657, 2014). "Despite the high frequency of the APOE-ɛ4 allele found in Africans, there was a general lack of association between the allele and dementia in the region." (PMID 25177512, 2014). "ApoE ε4 carriers, who are cognitively normal but at increased risk for AD, exhibited deficits in cerebral metabolic rate for glucose (CMRglu) in posterior cingulate (PCC) and parietal temporal cortex several decades prior to onset of dementia." (PMID 23555795, 2013). "When these effects were stratified by APOE allele status, there was not a significant reduction in incidence of all-cause dementia for any quartile of energy expenditure among APOE-ε4 carriers and non-carriers." (PMID 24961307, 2013). "In patients with dementia, the effects of sardilipin were very similar to those observed in patients with chronic dyslipidemia, suggesting that the lipid-lowering properties of sardilipin are APOE-dependent." (PMID 22482072, 2012). "In the absence of MCICC, risk factors for dementia include older age (P < 0.0001) and the presence of at least one APOE-4 allele (P = 0.0057)." (PMID 22536535, 2012). "We found that while ApoE ε4-carriers had a higher prevalence of dementia than non-carriers among PD patients, ApoE ε4 was associated with a statistically significant lower risk of PD (OR: 0.75, 95%CI: 0.59-0.94)." (PMID 21912625, 2011).